GIP (gastric inhibitory polypeptide)
Diseases named in the same sentence as GIP in open-access papers (continued):
Sharing a sentence is not in itself a finding about the gene and the disease.
diabetes (continued). "The GIP receptors (GIPRs) are severely down-regulated in diabetes, and the incretin effect of GIP is virtually abolished in diabetic subjects." (PMID 23967137, 2013). "The insulinotropic action of GIP virtually disappears in diabetes because of the severe down-regulation of GIPR in the pancreatic islets." (PMID 23967137, 2013). "It is well known that GLP-1 exerts insulinotropic action whereas GIP looses this action in diabetes." (PMID 22536426, 2012). "GIP has a potent stimulatory effect on insulin release from the pancreas, but several experimental studies have demonstrated that GIP looses this action in diabetes because GIP-R in pancreatic islets are substantially down-regulated in a hyperglycemic state." (PMID 22973260, 2012). "There is also growing evidence of GIP playing a protective role in both diabetes and AD and GIP is being investigated as a therapeutic target." (PMID 22279548, 2012). "Glucose levels fell in our vehicle-infused diabetic mice, whereas GIP infusion worsened the hyperglycemia in diabetes." (PMID 22536426, 2012). "This remains the only study so far examining the prolonged effects of GIP infusion on bone turnover markers in patients with diabetes, suggesting a possible tachyphylaxis of bone responsiveness following sustained exogenous GIP exposure, which warrants further investigation." (PMID 41596254, 2026). "Moreover, pharmacological GIP overcomes the impaired β‐cell response seen with endogenous GIP in people with diabetes, suggesting that it can exert beneficial metabolic effects when administered pharmacologically." (PMID 39540705, 2025). "Dysregulation of key gut hormones, including GLP-1, GIP, and amylin, may contribute to weight gain and complicate diabetes management." (PMID 40707821, 2025). "Additionally, tirzepatide, a dual GIP/GLP-1RA, enables unprecedented weight loss (>20%), reduces diabetes risk by over 90%, and improves outcomes in HF with preserved ejection fraction (HFpEF), MASLD, and obstructive sleep apnea." (PMID 39857719, 2025). "Moreover, tirzepatide is a dual GLP‐1RA/gastric inhibitory polypeptide (GIP) agonist with demonstrated efficacy in the treatment of diabetes." (PMID 40888511, 2025). "In addition, it has to be noted that the glucose-dependent insulinotropic polypeptide (GIP) has recently gained renewed interest for the treatment of diabetes due to the clinical success of the GIP/GLP-1 coagonist tirzepatide." (PMID 38681771, 2024). "A new addition to the drugs exploiting the incretin system, the glucose-dependent insulinotropic polypeptide (GIP)/GLP-1 dual agonist tirzepatide is among the furthest developed multi-agonists for diabetes care and has so far displayed promising nephroprotective effects." (PMID 38472620, 2024). "Also, for glucagon, an elevation is reported up to 6 months after RYGB, and GIP is mostly decreased after RYGB in individuals with diabetes mellitus." (PMID 39203840, 2024). "Dedicated studies are needed to investigate whether GIP still affects gallbladder motility in the presence of diabetes and whether these effects are replicated by TZP, as with endogenous GLP-1 and GLP-1RA." (PMID 39141075, 2024). "Subsequently, additional medications such as Metformin, DPP4is and dual GIP/GLP-1 receptor agonists may be further considered to optimise diabetes control." (PMID 39911238, 2024). "GLP-1 RA and GIP-GLP-1RA are now widely utilized in managing diabetes in type 2 diabetes mellitus." (PMID 38337487, 2024). "Furthermore, Tirzepatide has be the first dual agonist (GLP-1 and GIP Ra) to be licensed for diabetes therapy." (PMID 37904255, 2023). "On the other hand, GIP deficiency did not seem to be pathogenic of diabetes leading to the peptide being mostly ignored after initially being discovered and isolated." (PMID 37526853, 2023).
diabetes (continued). "More recently, novel co-agonists of GLP-1, glucose-dependent insulinotropic polypeptide (GIP) and glucagon have also been approved or are under evaluation for the treatment of diabetes and associated metabolic diseases, holding potential for cardiovascular risk reduction." (PMID 37542009, 2023). "In addition, a GIP analog has shown anti-apoptotic function and improved glucose tolerance in rat models of diabetes." (PMID 35909510, 2022). "In other words, considering the findings of our study as well as the results of other studies, it appears that changes in glucagon levels appearing after a meal in people with diabetes are not caused by endogenous GLP-1 or GIP." (PMID 34199839, 2021). "Instead, in subjects with T2DM the insulin secretion did not increase when compared with GLP-1 infusion alone, but there was an increase when compared with GIP and placebo administration, emphasizing the reduced insulinotropic effect of GIP in patients with diabetes." (PMID 35054422, 2021). "In conclusion, glutamine supplementation could improve glycemic control and levels of incretins (such as GLP-1 and GIP) in diabetes mellitus." (PMID 32983244, 2020). "A decline in GIP leads to a decline in bone metabolism, which could be one of the mechanisms that induces osteopenia in diabetics." (PMID 33033489, 2020). "The effects may be associated with hitherto unrecognized receptor interactions and, most recently, GIP/GLP-1 co-agonists have shown remarkable efficacies with concerning both weight loss and diabetes control." (PMID 33339298, 2020). "Interestingly, normalisation of glucose levels using insulin restores the incretin properties of GIP in diabetes." (PMID 32436022, 2020). "Since DPP-4 rapidly cleaves and inactivates the incretin hormones (GLP-1 and GIP), which are essential for glucose regulation, its blockade has been investigated as a way of ameliorating glycemia in diabetes through preservation of the impaired incretin action." (PMID 31366085, 2019). "Because of our careful monitoring of the mice and attempts to control for dopaminergic effects in other parts of the body, we conclude that the positive effect of dopamine inhibition on bone in diabetes is mostly likely due to a recovery in GIP signaling in osteoblasts." (PMID 31687648, 2019). "Furthermore, GLP-1 levels were higher in the diabetes group (p = 0.02), whereas leptin, glucagon, and GIP levels were similar between the two groups." (PMID 29467719, 2018). "The role of GIP in the development of diabetes and obesity is unclear, but hyperglycaemia may act to directly down-regulate GIP receptors in pancreatic b-cells leading to a defect in late-stage insulin release." (PMID 28780756, 2017). "Following an FDR correction for multiple comparisons, three markers remained significantly associated at the <5% level with a higher odds of self-reported diabetes at baseline: insulin, glucose-dependent insulinotropic peptide (or gastric inhibitory polypeptide; GIP) and pancreatic polypeptide (PP)." (PMID 28753646, 2017). "To understand the mechanism underlying the effects of ASCs on CAIA, we examined the serum levels of five cytokines (IL-15, IL-1α, IL-6, IL-7, and TNFα), five diabetes-related hormones (resistin, GIP, GLP-1, ghrelin, and leptin), and adiponectin using multiplex immunoassays." (PMID 26210906, 2015). "Since GLP-1 and GIP augment glucose-induced insulin release from pancreatic β-cells, suppresses glucagon secretion, and slows gastric emptying, incretins have been proposed as a potential therapeutic target for the treatment of patients with diabetes." (PMID 25582643, 2015). "Recent approaches in drug discovery have contributed to the development of new class of therapeutics like Incretin mimetics, Amylin analogues, GIP analogs, Peroxisome proliferator activated receptors, and dipeptidyl peptidase-4 inhibitor as targets for potential drugs in diabetes treatment." (PMID 26273667, 2015).
diabetes (continued). "It thus seems unlikely that GIP can exert its anti-atherogenic property in diabetes." (PMID 23967137, 2013). "Recently a published experimental study suggests that GIP could block the signal pathways of advanced glycation end products (AGEs) in HUVECs, which play a crucial role in vascular damage in diabetes." (PMID 22973260, 2012). "There was a significant interaction between circulating GLP-1 and GIP, serum high-density lipoprotein cholesterol, triglyceride, and serum uric acid concentrations but not waist circumference, fasting glucose, HbA1c, or presence of diabetes." (PMID 20470376, 2010). "It is also likely that glucagon-like peptide-1 (GLP-1) and glucose-dependent insulinotropic polypeptide (GIP) agonists will play a greater role in the management of PCOS as these medications become ever more widely used for weight loss and the management of metabolic syndrome and diabetes." (PMID 40182629, 2025). "Hence, the impaired insulinotropic action of GIP may reflect impaired β-cell function and may be secondary to diabetes and β-cell failure." (PMID 40024571, 2025). "Tirzepatide, a dual GIP and GLP-1 receptor agonist, has recently been approved for the treatment of patients with diabetes; it has resulted in superior HbA1c reduction in diabetes patients and exhibited unprecedented weight loss in obese individuals compared with GLP-1 receptor agonists alone." (PMID 39273671, 2024). "Therefore, our present study suggests that the GIP-GIP receptor axis may exert anti-atherosclerotic actions by suppressing AGE-RAGE-induced foam cell formation in diabetes." (PMID 39273671, 2024). "Therefore, GLP-1 accounts for more than GIP in studies of diabetes based on the incretin system." (PMID 35629891, 2022). "Therefore, we hypothesize that GIP and its role in glucose metabolism could be a pathogenic factor linking ADHD and metabolic disorders such as diabetes." (PMID 36151371, 2022). "The results of our current study suggest that GIP may play a role in prolonged diabetes control." (PMID 34789863, 2021). "If the association of GIP gene and CAD was proved, a tentative inference on this conclusion is that the mechanism of GIP gene influencing the risk of CAD might be independent of the development of diabetes." (PMID 28840129, 2017). "Interestingly, the decreased GIP expression levels noted in the present work is coherent with previous studies on insulin resistance and T2D, reporting reduced β-cell responsiveness to GIP and lower postprandial GIP circulating levels in diabetes." (PMID 26376914, 2015). "We examined whether GIP can exert anti-atherogenic effects in diabetes." (PMID 22536426, 2012). "This suggests that GIP may modulate the processes of STZ-induced diabetes." (PMID 22536426, 2012). "This may explain the inability of GIP to induce insulin secretion in diabetes." (PMID 22536426, 2012). "Additionally, since activation of receptors for GLP-1 and GIP exerts pro-survival effects on β-cells, incretins may also be capable of maintaining β-cell mass in diabetes." (PMID 20231880, 2010). "It is a dual glucose-dependent insulinotropic polypeptide (GIP) and GLP-1 receptor agonist, enhancing its ability to manage diabetes." (PMID 40430487, 2025). "Exogenous GIP infusion has also been shown to reduce serum CTX levels in both healthy individuals and patients with diabetes." (PMID 41516077, 2025). "Recent case series and retrospective analyses have also reported on the use of tirzepatide, a dual glucose-dependent insulinotropic polypeptide (GIP)/GLP-1 receptor agonist, in adult patients with lipodystrophy presenting with diabetes." (PMID 40842493, 2025). "Several diabetes drugs have been trialed as management strategies for HFpEF, including the GIP (glucose-dependent insulinotropic polypeptide) and GLP1 agonists—semaglutide and tirzepatide—and SGLT inhibitors—dapagliflozin and empagliflozin." (PMID 41226834, 2025).
diabetes (continued). "Glucose-dependent insulinotropic polypeptide (GIP) and glucagon-like peptide-1 (GLP-1) exert their beneficial effects on diabetes through distinct G protein-coupled receptors, which are highly expressed on islet β cells." (PMID 40108027, 2025). "By inhibiting DPP-4 enzyme activity, these agents potentiate the actions of incretin hormones, namely glucagon-like peptide-1 (GLP-1) and gastric inhibitory polypeptide (GIP), addressing key pathophysiological aspects of diabetes." (PMID 39737272, 2024). "The efficacy of GIP/GLP1 receptor co-agonists on glucose control is surprising, and allows to reach glucose levels similar to diabetes remission in a greater percentage of patients compared to other treatments." (PMID 38831203, 2024). "Since their incretin effect is diminished in diabetes, both GLP and GIP are of therapeutic importance in its treatment." (PMID 38782979, 2024). "This diabetes drug acts as a dual agonist for GLP1R and the glucose-dependent insulinotropic polypeptide (GIP) in humans but acts as a potent GLP1R agonist in rodents." (PMID 39007271, 2024). "The dual GIP/GLP-1 receptor co-agonist, tirzepatide, for diabetes therapy has opened a new era on personalized glycemia control and weight loss in a safe manner with broad and promising clinical implications." (PMID 37904255, 2023). "The Tirzepatide, a dual GIP/GLP-1 receptor co-agonist, for diabetes therapy has opened a new era on personalized glycemia control and weight loss in a safe manner with broad and promising clinical implications." (PMID 37904255, 2023). "PPAR, GIP, FFA1, melatonin are the recent targets that already in the focus for developing new therapies in the treatment of diabetes." (PMID 36782201, 2023). "Tirzepatide now is the first peptide dual agonist targeting GIP and GLP-1 receptors approved for the therapy of diabetes in the USA, Europe, and the UAE." (PMID 36050763, 2022). "Gliptins are drugs for the treatment of diabetes mellitus (type II) by inhibiting DPP4, the enzyme that inactivates glucose-dependent insulinotropic polypeptide (GIP)." (PMID 34360322, 2021). "Dipeptidyl peptidase 4 (DPP-4) inhibitors are widely used as therapeutic agents for diabetes mellitus, reducing serum glucose levels by inhibiting glucagon--like peptide--1(GLP-1) and gastric inhibitory polypeptide (GIP) degradation." (PMID 32489704, 2020). "In conclusion, the present study allowed identifying a novel positive regulatory link between HNF4α (MODY1) and GIP incretin in the intestine and paves the way for further studies as to whether this molecular relationship may be therapeutically exploited in metabolism disorders including diabetes." (PMID 30862908, 2019). "Further work to create relevant genetic mouse models are planned to further investigate the newly discovered relationships between diabetes, GIP, dopamine, LOX, and bone structure in diabetes." (PMID 31687648, 2019). "This is in agreement with our results, which showed a reduction in DPPIV activity in patients with diabetes but incretins levels were higher only in OW group for GLP1 and ObI and ObII/III groups for GIP." (PMID 28425473, 2017). "We therefore measured the incretin hormone GIP in 17 RFX6 heterozygotes (eight with diabetes) and compared to 26 controls (two with diabetes)." (PMID 29026101, 2017). "Diabetes medication status, biochemical and hormonal data including blood glucose, HbA1c, insulin, C-peptide, HOMA-IR, ghrelin, leptin, GLP-1, PYY, and GIP were evaluated for 12 months after surgery." (PMID 29216250, 2017). "One prevalent role of CD26 in autoimmune diseases such as diabetes is via the enzymatic activity, which inactivates peptides (GLP-1 and GIP) critical for stabilizing blood glucose levels." (PMID 29213079, 2017). "Age, sex, BMI, reconstruction type, diabetes duration, preoperative blood glucose, HbA1c, insulin, C-peptide, HOMA-IR, ghrelin, leptin, GIP, PYY, and GLP-1 were analyzed." (PMID 29216250, 2017).
diabetes (continued). "Because GIP and GLP-1 are rapidly inactivated by DPP4, DPP4 inhibitors are widely used for clinical treatment of diabetes as an insulin secretagogue." (PMID 27053237, 2016). "In contrast to GIP, the secretion of GLP-1 is reduced in obese subjects without diabetes, suggesting that incretin secretion is altered in the early stages of diabetes." (PMID 26075286, 2015). "Based on these results, this seaweed can be used as alternative therapy for diabetes by raising the levels of endogenous incretin hormones (GLP-1 and GIP)." (PMID 25050371, 2014). "The current studies evaluated the effects of a truncated GIP analog, D-Ala2-GIP1–30 (D-GIP1–30), on glucose homeostasis and β-cell mass in rat models of diabetes." (PMID 20231880, 2010). "In diabetes it cleaves the N-terminal tyrosine-proline dipeptide from the glucagon-like peptide-1 (GLP-1), glucose-dependent insulinotropic polypeptide (GIP), gastric inhibitory peptide, and pituitary adenylate cyclase activating peptide (PACAP)." (PMID 20462426, 2010). "Although GIP is believed to contribute at least as much as GLP-1 to the incretin effect under normal physiological conditions, the situation is complicated by the different insulinotropic efficiencies of GIP and GLP-1 in the context of diabetes." (PMID 20204054, 2010). "Tirzepatide, an agonist of the glucose-dependent insulinotropic polypeptide (GIP) and GLP-1 receptor, has shown promising weight-loss effects in patients with and without diabetes." (PMID 39826021, 2025). "Whilst the results of cardiovascular outcome studies are awaited, the GLP‐1/GIP RA tirzepatide has been shown to significantly improve surrogate markers of cardiovascular disease in people with and without diabetes mellitus." (PMID 39781571, 2025). "In vivo, intravenous infusion of GIP suppresses serum C-terminal telopeptide of type I collagen (CTX-1) levels, a biochemical marker reflecting the rate of osteoclastic bone resorption in patients with diabetes and their healthy counterparts." (PMID 41516077, 2025). "Medications such as Sodium-Glucose Cotransporter 2 inhibitor (SGLT2i), Glucagon-Like Peptide 1 Receptor Agonist (GLP-1RA), and the novel dual glucose-dependent insulinotropic polypeptide (GIP) and GLP-1 receptor agonist, tirzepatide, have revolutionized diabetes treatment paradigms." (PMID 39335551, 2024). "One of the recent advances in diabetes treatment is the discovery of the incretin-insulin pathway, which involves two hormones: glucagon-like peptide-1 (GLP-1) and glucose-dependent insulinotropic polypeptide (GIP)." (PMID 38523307, 2024). "The protective effects of GIP on the bone have been also observed in humans with and without diabetes." (PMID 38831203, 2024). "In this study, food diaries and frozen blood samples were collected from the Baltimore Longitudinal Study of Aging (BLSA) participants, who underwent an oral glucose tolerance test (OGTT) and had no diabetes, and analyzed for glucose, insulin, and GIP levels." (PMID 38276259, 2023). "Patients with diabetes seem to have a lower response to GIP regardless of the concentration of the hormone." (PMID 37526853, 2023). "Current studies have shown that patients with pre-diabetes or type 2 diabetes mellitus often have defects in the effect of incretin, while exogenous GIP does not show a good insulin-promoting effect." (PMID 36583004, 2022). "Sitagliptin is a highly selective inhibitor of dipeptidyl peptidase-4 (DPP-4) and is used for the treatment of diabetes by inhibiting the activity of DPP-4 and prolonging the bioactivity of glucagon-like peptide −1 (GLP-1) and gastric inhibitory polypeptide (GIP)." (PMID 35635037, 2022). "Then, in subjects with diabetes, a lack of GIP amplification of the late phase insulin response to glucose was observed." (PMID 35054422, 2021).